DES (desmin)
Diseases named in the same sentence as DES in open-access papers (continued):
Sharing a sentence is not in itself a finding about the gene and the disease.
tumor (continued). "Immunostaining showed that the tumor was positive for the Vimentin, Desmin and MyoD1, and was negative for CK, P63, NSE, CD45, CD30, S-100, CD99, Myoglobin, CD68, CD34, CD31, and α–SMA." (PMID 23379991, 2013). "Immunohistochemically the tumor cells express desmin, SMA and vimentin but not S-100 or cytokeratin." (PMID 23421917, 2013). "Immunohistochemically, the tumor cells were focally positive for S-100 protein, but negative for desmin, CD34 and EMA." (PMID 24294990, 2013). "Cytokeratin 5/8 and Desmin antibodies did not stain tumor sections of β-catΔ/Δ mESC lines, in contrast to β-catfl/fl and res-β-catΔ/Δ teratomas in which approximately 10–40% of the cells were positively stained." (PMID 23691006, 2013). "Immunostaining showed that the tumor was strongly positive for Vimentin, Desmin and MyoD1, and was negative for CK, P63, NSE, CD45, CD30, S-100, CD99, Myoglobin, CD68, CD34, CD31, α–SMA." (PMID 23379991, 2013). "Immunoperoxidase staining showed that the main tumour cells expressed desmin and lacked S100 expression." (PMID 24459597, 2013). "The tumor cells were negative for desmin (1:200; Cell Marque, Manchester, UK), suggesting myofibroblastic differentiation." (PMID 23742153, 2013). "Tumor cells expressed focal cytokeratin (1 : 150, clone: AE1/AE3, DAKO Cytomation, USA), EMA (1 : 20, clone: sc-9121, Santa Cruz Biochemicals, USA), and, unexpectedly, desmin (clone: DE-R-11, Leica Bond, UK) positivity." (PMID 22966471, 2012). "Immunohistochemically, the tumor cells are positive for SM-actin and desmin, but negative for myoglobin and S-100 protein; 4) Rhabdomyosarcoma, especially embryonal rhabdomyosarcoma, is composed of undifferentiated rounded and spindle cells." (PMID 22515616, 2012). "The tumor cells showed focal cytokeratin, EMA, and, unexpectedly, desmin positivity." (PMID 22966471, 2012). "Moreover, as determined by staining for mesenchymal cells, such as pericytes (desmin) and smooth muscle cells of chicken blood vessels (ASMA), reactive responses of the chicken stroma to the invading tumor cell front were nearly abolished." (PMID 23110550, 2012). "The diagnosis was initially suspected to be adult rhabdomyoma, but the tumor cells were negative for immunostaining of desmin, muscle actin (HHF35), α-smooth muscle actin (α-SMA) and myoglobin and positive for periodic acid-Schiff with diastase (PAS-D)." (PMID 21299893, 2011). "Immunoreactivity of the tumor cells with HMB45 and desmin will help clinch the diagnosis." (PMID 21789263, 2011). "The initial diagnosis was ruled out by immunohistochemical analysis that showed that tumor cells were negative for desmin, HHF35, α-SMA and myoglobin and positive for PAS-D." (PMID 21299893, 2011). "Immunohistochemical analyses indicated that many of the tumor cells were positive for vimentin, while tumor cells were negative for cytokeratins, desmin, S-100 protein, actins, c-kit, and CD34." (PMID 21288322, 2011). "In our study there was a significantly higher level of desmin expression in stage III tumors when compared to both stage I and II tumors, suggesting a higher level of mature microvasculature in the late stage tumor tissue or a higher level of desmoplasia (or both)." (PMID 22141345, 2011). "Instead, the tumor cells showed striking CD99, synapthophysin and desmin immunoreactivity." (PMID 20598147, 2010). "Immunohistochemically, the tumour cells express vimentin, desmin, smooth muscle actin, and muscle specific actin, but not cytokeratin, neurofilament, or glial fibrillary acidic protein." (PMID 19068127, 2008). "Differential expression analysis of the metastatic and primary tumor samples shows that a large number of the most highly downregulated genes such as TAGLN, ACTG2, TPM1, MYH111 and DES have been previously identified as expressed mostly in the prostatic stromal cells." (PMID 17430594, 2007). "The tumor was negative for desmin, S-100, CD 34 and c-kit (CD117) but focally positive for actin on immunohistochemistry (IHC)." (PMID 15638946, 2005).
tumor (continued). "On immunohistochemistry, multiple sections were negative for CD-34, CD-117, S-100 and desmin but focally positive for actin as in the initial tumor." (PMID 15638946, 2005). "If the degree of expression of desmin is related to myogenic differentiation, then our results indicate that poorly differentiated RMS tend to have a better prognosis than the well differentiated tumours." (PMID 3311112, 1987). "For example, ovarian cancer-derived EVs upregulate CAF markers such as α-SMA, vimentin, desmin, and FSP-1 to facilitate normal fibroblasts to CAF-like transformation, thereby upregulating their motility, proliferation, invasiveness, and the pro-tumor crosstalk between tumor cells and CAFs." (PMID 40908470, 2025). "The tumor cells were negative for S-100 protein, desmin, and muscle-specific actin (MSA)." (PMID 41010284, 2025). "Tumours were stained negative for desmin, E-cadherin, neurofilament and BCL10." (PMID 41007613, 2025). "Immunohistochemistry showed that tumor cells were CAM5.2 (+), AE1/3 (+), Ber-EP4 (–), EMA (+), CD45 (+), NSE (+), Synaptophysin (–), Chromogranin A (–), CD56 (+), NKX2.2 (–), Vimentin (+), GFAP (–), S-100 (–), Desmin (–), SMA (–), WT1 (–), MyoD1 (–), Myogenin (–)." (PMID 40034204, 2025). "Next, we showed that hRAT-CMs increase the expression of mesenchymal markers, like desmin, N-cadherine and vimentin, in both tumor and non-tumor renal epithelial cells and that AT can stimulate the epithelial-mesenchymal transition (EMT) and therefore the metastatic capacity of cells." (PMID 40995093, 2025). "The tumor cells demonstrated diffuse positivity for vimentin, while desmin was negative." (PMID 39473659, 2024). "The tumours tend to lack smooth muscle differentiation and are usually negative for desmin and h-caldesmon but may show focal positivity for SMA." (PMID 38151535, 2024). "However, those areas comprised less than 1% of the entire tumor volume, and most tumor tissues did not express desmin." (PMID 38248037, 2024). "Tumor cells express desmin and CD34 but are negative for CD99, Bcl-2, and STAT6." (PMID 39206171, 2024). "In the IHC study, tumor cells showed positivity for CD99, EMA, vimentin, and TLE1, while they were negative for NKX2.2, WT1, BCOR, PDGFA, cytokeratins, muscle markers (smooth muscle actin, desmin, caldesmon, MyoD1, and myogenin), and melanocytic markers (HMB45, SOX10, and S100)." (PMID 38339014, 2024). "Several growth factors secreted by tumor cells, such as PDGF-B, VEGF-A, and TGFβ-1, may trigger the prevalence of a PDGFRβ+/desmin+ pericyte phenotype through the acquisition of αSMA, RGS5, NG2, and desmin immunopositivity in activated pericytes at BCBM sites." (PMID 35455945, 2022). "(Immunohistochemical stains showed that the tumor cells were positive for desmin and TFE3, while negative for pancytokeratin, CAM5.2, EMA, chromogranin, synaptophysin, NSE, CD45, SMA, HHF35, myogenin, CD117, DOG1, MUC4, S100, SOX10, HMB45, Melan-A, CD31, ERG, TLE1, STAT6, and Cathepsin-K)." (PMID 35001360, 2022). "Sarcomatoid carcinoma cells were partially positive for AE1/AE3 and strongly positive for vimentin, whereas all the tumor cells were negative for neuroendocrine markers and other mesenchymal markers, such as desmin, SMA, myglobin, mygenin, S-100, DOG-1, CD34, CD117, CD15, CD30, and CD20." (PMID 33761637, 2021). "On immunohistochemistry, the tumor cells had typically strong and diffuse positivity for vimentin and BCL2, focal positivity for CD34, and weak diffuse positivity for CD99 but negativity for cytokeratins AE1–AE3, actin HHF35, actin 1A4, calponin, caldesmon, desmin, S-100 protein, and collagen IV." (PMID 34211794, 2021).
tumor (continued). "Tumor cells did not express Desmin, Synaptophysin (SYP), Chromogranin and S100." (PMID 34508517, 2021). "The tumor cells were strongly positive for S-100 protein and negative for Desmin." (PMID 32669088, 2020). "Immunohistochemically, the tumor cells were positive for vimentin, epithelial membrane antigen, calponin, and were partially mild to moderate positive for estrogen receptor, but completely negative for S100 protein, glial fibrillary acidic protein, CD34, desmin, SMA and cytokeratin." (PMID 31915021, 2020). "Evidence of neoplasia in BE and EAC was characterized by reduced gastrointestinal epithelium markers keratin 13 and keratin 20, relative to RE, while epithelial-to-mesenchymal transition markers vimentin and desmin were increased in BE and EAC respectively, compared to control." (PMID 32650561, 2020). "Moreover, the expression levels of myofibrillar proteins including myosin heavy chain (MyHC), actin, Tm, TnI, fTnT, and desmin were not altered by tumor-bearing and/or ECC training." (PMID 29894511, 2018). "Moreover, a FBRC tumor is almost invariably positive for keratin and/or desmin, whereas the tumor in our case was entirely negative for pan-keratin and/or desmin." (PMID 28018701, 2016). "The tumor cells are negative for desmin, α-SMA, CD34, and S-100 protein." (PMID 26090253, 2015). "Immunostains on tumor biopsy were positive for SMA and calretinin (focal in epithelioid nests) and negative for cytokeratins (Ck-AE1/AE3 and CK5/6), TTF-1, mammaglobin, breast gross cystic disease fluid protein-15, estrogen/progesterone receptors, CD34, and desmin." (PMID 25977823, 2015). "The myoid tumor markers such as actin-sm and desmin were negative in this case." (PMID 26315812, 2015). "However, the tumor cells were negatively stained for myoglobin, SMA, desmin and S-100." (PMID 24959221, 2014). "The tumor was negative for leukocyte common antigen, desmin, and myogenin." (PMID 25144312, 2014). "Staining for AE1/AE3, S-100, smooth muscle actin (SMA), desmin, cluster of differentiation 31 (CD31), CD34 and anaplastic lymphoma receptor tyrosine kinase (ALK) was negative, while the staining for vimentin was strongly positive (+++) with >50% positive tumor cells." (PMID 24959221, 2014). "Immunohistochemical analysis of the tumor in our case revealed diffusely positive immunoreactivity for C-kit (CD 117), tyrosine kinase growth factor receptor, and CD 34 but negative immunoreactivity for smooth muscle actin, Desmin, and S-100 protein." (PMID 26425588, 2013). "Furthermore, the lack reaction of Syn, CgA, S-100, NSE, CD34, and Desmin supported the origin of tumor cells from pulmonary epithelium, rather than neuroendocrine, vascular-endothelium, or myoepithelium." (PMID 23587094, 2013). "The tumor was negative with Bcl-2, desmin, HMB-45, S100, FVIII, and CD31." (PMID 23662242, 2013). "In addition, the tumor cells are negative for skeletal muscle proteins, such as desmin and myoglobin, and are positive for S-100 protein; 2) In malignant fibrous histiocytoma, the tumor is composed of spindle cells and giant tumor cells." (PMID 22515616, 2012). "PECs are hybrid tumor cells characterized by immunoreactivity for both melanocytic and smooth muscle markers, such as HMB45, HMSA-1, MelanA/Mart1, microphthalmia transcription factor (Mitf), actin, and, less commonly, desmin; the immunoreactivity for vimentin is usually inconspicuous." (PMID 22957287, 2012). "There is considerable variability in pericyte characteristics between tumor types, with some studies reporting that mature pericytes are PDGFR-β negative and desmin positive, while other studies report that tumor pericyte populations can have overlapping markers." (PMID 22007215, 2012). "The tumor cells were negative for calretinin, desmin, muscle actin, and CK7." (PMID 22008415, 2011). "The tumor cells were negative for calretinin, desmin, and muscle actin." (PMID 22008415, 2011).
tumor (continued). "Additionally, Cytokeratin 7 and 20, CD56, synaptophysin, chromogranin, SF1, α-inhibin, WT1, desmin, SMA, GATA3, Uroplakin II, CD10, PR, CD5, BerEP4, and NUT were negative in tumor cells, no loss of INI1 expression, β-catenin showed only membranous staining without nuclear accumulation (no shown)." (PMID 37518334, 2023). "However, the spindle tumor component was diffusely strongly positive for vimentin and negative for AE1/AE3, whereas all the tumor cells were negative for neuroendocrine markers and other mesenchymal markers, such as desmin, SMA, myglobin, mygenin, S-100, DOG-1, CD34, CD117 and." (PMID 33761637, 2021). "The varying results could be due to the fact that these studies were performed on tissue that had not been laser microdissected: the strong desmin expression by smooth muscle cells of the muscularis mucosae and muscularis propria would mask any differences between tumor and normal epithelium." (PMID 22141345, 2011). "The tumor was positive for CD99, SATB2, TLE1, cyclin D1, and focal FLI1, while negative for EMA, S100, desmin, calponin, and SOX10." (PMID 41869091, 2026). "The tumor was negative for cytokeratin AE1/AE3, p63, desmin, CD34, S100, glial fibrillary acidic protein (GFAP), and SOX10." (PMID 40766037, 2025). "Tumour cells were strongly positive for CD204, Iba1 and desmin, and negative for CD31 and smooth‐muscle actin (SMA)." (PMID 39814065, 2025). "In this case, spindle and stellate tumor cells were strongly positive for vimentin and CD34, and negative for CK, desmin, SMA, HMB-45, MDM2, CDK4, p16, β-catenin, and STAT6." (PMID 41458523, 2025). "We acknowledge that immunohistochemical markers such as SMA, desmin, caldesmon, TTF-1, and Napsin A are not entirely specific to their respective tumor types." (PMID 40666089, 2025). "Repeat immunohistochemical staining revealed tumor cells positive for CD34 and p16, and negative for smooth muscle actin, desmin, S100, and SOX10, except for the lipoblasts, which were positive for S100 and SOX10." (PMID 40677885, 2025). "Immunohistochemistry was vital in establishing the diagnosis, as the tumor cells were positive for SMA and negative for desmin, CD34, S100, and keratin, in line with the typical MPC immunophenotype." (PMID 40230760, 2025). "Immunohistochemical studies revealed that the tumor cells tested positive for beta-catenin, with nuclear staining, and negative for CD34, CD117, desmin, and S100." (PMID 39278889, 2025). "Most studies have demonstrated that tumor cells express S-100, CD68, and Vimentin, whereas markers such as CK, Syn, CgA, Desmin, and pituitary hormones are typical negative, with the majority of cases also showing negativity for GFAP." (PMID 40860841, 2025). "The tumor cells tested negative for CD117, anaplastic lymphoma kinase, and pan-cytokeratin and positive for smooth muscle actin, vimentin, and desmin." (PMID 40761993, 2025). "The tumor cells were negative for CKpan, P63, CK5/6, C-erB-2, CD117, DOG-1, smooth muscle actin (SMA), Desmin, and synaptophysin." (PMID 39889177, 2025). "The immunophenotype of the tumor did not reveal a clear line of origin, with negative staining for GFAP, OLIG2, S100 protein, SOX10, desmin, pankeratin, synaptophysin, and only focally positive vimentin." (PMID 40159593, 2025). "Immunohistochemical examination showed that tumor cells were strongly positive for vimentin, SMA, and P16 but negative for desmin, CK, P40, P63, CK5, HMB45, MyoD1, myogenin, S100, and SOX10." (PMID 39872225, 2025). "Tumour cells expressed vimentin, S-100 and NSE and were negative to CD3, CD20, CD79a, MHC II, MUM1, desmin, c-Kit, pancytokeratin and α-SMA." (PMID 40045318, 2025). "Tumor cells in PHL characteristically express smooth muscle markers such as SMA, desmin, and caldesmon, while being negative for markers of epithelial, neural, and gastrointestinal stromal differentiation." (PMID 41583212, 2025).
tumor (continued). "Immunohistochemically, the tumor cells were positive for CD34 and negative for smooth muscle actin, desmin, SOX10, S100, EMA, MUC4, and STAT6." (PMID 40677885, 2025). "Immunohistochemical studies revealed tumor cell positivity for smooth muscle actin (SMA), desmin, and caldesmon, with negative staining for cytokeratin, DOG1, and CD117." (PMID 41583212, 2025). "In our case, the tumor cells were positive for CD34 and CD99 while negative for smooth muscle Actin, Desmin and S100." (PMID 40709355, 2025). "The IHC findings showed the spindle-shaped tumor cells that were positive for SMA, desmin, and negative for KIT, CD34 (data not shown)." (PMID 40625542, 2025). "Immunohistochemistry supports the diagnosis: tumor cells are vimentin-positive, show focal/patchy SMA reactivity, and are generally negative for desmin, cytokeratins, and S-100." (PMID 41227209, 2025). "Immunohistochmical staining of SCCOHT tumor tissues frequently demonstrates the expression of EMA, cytokeratin, and calretinin, while typically lacking α-inhibin, S100, desmin, and thyroid transcription factor-1." (PMID 40071085, 2025). "The immunohistochemical examination showed that the tumor cells were positive for CD34 and CD99 while negative for smooth muscle Actin, Desmin, and S100." (PMID 40709355, 2025). "Immunohistological examination showed that the tumor cells were positive for EMA and negative for cytokeratin AE1/AE3, p63, desmin, CD34, S100, GFAP, and SOX10." (PMID 40766037, 2025). "The tumor cells were diffusely CD34, ERG, and focally p63 reactive, while S100 protein, cytokeratin AE1/AE3, Pan-TRK, ALK, smooth muscle actin, and desmin were negative." (PMID 40878874, 2025). "Immunohistochemically, the tumor cells are negative for CD117/c-KIT, discovered on GIST 1, CD34, desmin, and S100." (PMID 40761993, 2025). "Tumour cells showed cytoplasmic expression of vimentin and α-SMA and were negative to desmin, S-100 and c-Kit." (PMID 40045318, 2025). "The pathology showed the tumor cells to be positive for cytokeratin (CK), Vimentin, EMA, CD34, cyclinD1, negative for CK8, CK19, CK20, SMA, Desmin, S-100, CD117, Dog-1, Hepar-1, SOX-10 and ALK, and Ki-67 approximately 50%, which confirmed the diagnosis of SHC." (PMID 38552058, 2024). "Tumor cells were negative for epithelial markers AE1/AE3 and CAM5.2, and also negative for p40, NUT, chromogranin, desmin, NKX2.2, S100, SOX10, HMB45, GATA3, CD45 (LCA), CD3, and CD20, with intact INI1 and BRG1 nuclear expression." (PMID 39404971, 2024). "The tumor cells were negative expression of CgA, CD56, CK5/6, CK20, Myogenin, MyoD1, Desmin, CEA, S100, CK8/18, CDX2, CD20, CD5, CD3, CD79a, LCA and HMB45." (PMID 38877473, 2024). "The tumor showed a strong positive expression for the S-100 marker, thus confirming its neural origin.The tumor showed negative expression for SMA and Desmin, ruling out the possibility of myofibrosarcoma." (PMID 39713108, 2024). "Immunohistochemical analysis showed the tumor was positive for αSMA and muscle-specific actin (HHF-35) and negative for desmin." (PMID 39816285, 2024). "Nuclear fission is easy to see.Immunohistochemical results show that the tumor cells diffusely express Nestin, a-SMA, SDHB, a small amount of CD34, and CD117, DOG-1, Calponin, h-Caldesmon, Desmin, S-100 and pan-cytokeratin (CKpan) are all negative." (PMID 38388419, 2024). "While this tumour was h-caldesmon negative, a small number of tumour cells were positive for SMA and desmin." (PMID 38151535, 2024). "In this case, the tumor cells were negative for SMA and Desmin in IHC, which led to the final diagnosis of the case as APH." (PMID 39867882, 2024). "Tumor cells in case 3 of our study were positive to vimentin and CD99 but they were negative to S-100, desmin, HHF-35, SMA, CD31, CD34, STAT-6 and pan-cytokeratin (AE1/AE3)." (PMID 39462411, 2024). "The vessels that proliferated in the tumour were highlighted by CD31, CD43 and the tumour cells were negative for HMB45, SMA, Desmin and CEA." (PMID 39816396, 2024).